SLC37A3 (solute carrier family 37 member 3)
Description:
Unlike the other SLC37 members, lacks glucose-6-phosphate antiporter activity. In osteoclasts, forms a transporter complex with ATRAID for nitrogen-containing-bisphophonates (N-BPs) required for releasing N-BP molecules that have trafficked to lysosomes through fluid-phase endocytosis into the cytosol.
Synonyms: SPX3; DKFZp761N0624
Tractability: Antibody: UniProt predicts a signal peptide or a membrane-spanning region.
Gene: Protein-coding gene on chromosome 7 (140,293,693 to 140,404,433, reverse strand). Ensembl gene ENSG00000157800.
Subcellular location: Endoplasmic reticulum membrane; Lysosome membrane
Gene Ontology:
Molecular function: glucose 6-phosphate:phosphate antiporter activity; protein binding; xenobiotic transmembrane transporter activity; transmembrane transporter activity
Biological process: glucose-6-phosphate transport; phosphate ion transmembrane transport; xenobiotic transmembrane transport; transmembrane transport
Cellular component: endoplasmic reticulum membrane; lysosomal membrane; membrane
Genetic constraint (gnomAD): Loss-of-function variants: 51 observed, 63.19 expected, observed/expected ratio (o/e) 0.81, 90% interval 0.64 to 1.02. The upper end of that interval is the gene's LOEUF score, 1.02, which puts it in group 4 of 6, group 1 being the genes least tolerant of losing a copy. Missense variants: 497 observed, 615.73 expected, observed/expected ratio (o/e) 0.81, 90% interval 0.75 to 0.87. Synonymous variants: 208 observed, 238.28 expected, observed/expected ratio (o/e) 0.87, 90% interval 0.78 to 0.98.
Homologues: Orthologues: chimpanzee SLC37A3 (100% identical), macaque SLC37A3 (98% identical), dog SLC37A3 (92% identical), pig SLC37A3 (89% identical), Caenorhabditis elegans T11G6.2 (44% identical), Caenorhabditis elegans T11G6.4 (42% identical), Drosophila melanogaster MFS16 (33% identical), Drosophila melanogaster Picot (16% identical), Drosophila melanogaster CG9254 (15% identical), Drosophila melanogaster dmGlut (15% identical), Drosophila melanogaster CG6978 (15% identical). Paralogues in human: SLC37A1 (35% identical), SLC37A2 (34% identical), SLC17A5 (16% identical), SLC17A7 (16% identical), SLC17A8 (16% identical), SLC17A6 (15% identical), SLC37A4 (14% identical), SLC17A4 (14% identical), SLC17A2 (14% identical), SLC17A3 (13% identical), SLC17A1 (13% identical), SLC17A9 (13% identical).
Diseases named in the same sentence as SLC37A3 in open-access papers:
SLC37A3 is named in the same sentence as 10 diseases in open-access papers, as found by Europe PMC text mining. Sharing a sentence is not in itself a finding about the gene and the disease. The quoted sentences say what the papers report.
congenital hyperinsulinism (1 paper, 2018). "SLC37A1 seems to be required for lipid biosynthesis in cancer cell lines, SLC37A2 has been proposed as a vitamin D and a phospho-progesterone receptor target gene, while mutations in the SLC37A3 gene appear to be associated with congenital hyperinsulinism of infancy." (PMID 29719821, 2018). "In this latter regard, the human SLC37A3 gene could contribute to the pathogenesis of congenital hyperinsulinism of infancy (CHI)." (PMID 29719821, 2018).
Hyperinsulinemia (1 paper, 2015). An increased concentration of insulin in the blood. "We also observed a correlation between change in DNA methylation in SLC37A3 (cg15751131, ∆beta −0.10), a sugar-phosphate exchanger for which an association with congenital hyperinsulinemia has recently been reported, and fasting glucose (R = −0.80)." (PMID 25651499, 2015).
Sepsis (1 paper, 2021). Sepsis is defined as life-threatening organ dysfunction caused by a dysregulated host response to infection. "We performed feature selection analysis and found that combination of three genes (TLCD4, PRSS30P, and ZNF493) and seven genes (TLCD4, PRSS30P, ZNF493, AGO2, SLC37A3, SLC2A1, and RPL11) showed moderate performance in identifying patients with sepsis and ARDS within 1 day after admission." (PMID 33818300, 2021).
cancer (4 papers, 2018 to 2025). A tumor composed of atypical neoplastic, often pleomorphic cells that invade other tissues. "SLC37A3, an endoplasmic reticulum (ER)‐associated sugar‐phosphate/phosphate exchanger, has not been previously reported in cancers." (PMID 40056063, 2025). "Polymorphisms were also found in other canonical cancer-related genes, including SLC37A3, BAZ1A, SRP54, MYH1 and ABCC1, but were not directly involved in MASLD pathogenesis." (PMID 38540416, 2024).
SLC37A3 also shares sentences with these, for which no sentence is quoted: Chronic Lymphocytic Leukemia (1 paper); glioblastoma (1); GM2 gangliosidosis (1); low grade glioma (1); Obesity (1); tumor (1).